IGF2BP3 (insulin like growth factor 2 mRNA binding protein 3)
Diseases named in the same sentence as IGF2BP3 in open-access papers (continued):
Sharing a sentence is not in itself a finding about the gene and the disease.
leukemia (continued). "IGF2BP3 has been reported also as an oncogenic factor implicated in the transcription and splicing of MLL target genes in MLL-mAf4 mediated leukemia as its knockout impaired leukemogenesis in a mouse disease model." (PMID 36335100, 2022). "Here, we identified that IGF2BP3 is specifically overexpressed in acute myeloid leukemia (AML), a subtype of leukemia associated with poor prognosis and high genetic risk." (PMID 35217832, 2022). "Here, we determined Igf2bp3 is required for the efficient initiation of MLL-Af4-driven leukemia and function of LICs." (PMID 34321607, 2022). "To understand the overlap of transcriptional and posttranscriptional regulation in MLL-rearranged leukemia, we compared IGF2BP3-regulated targets with a published MLL-Af4 ChIP-Seq dataset." (PMID 34321607, 2022). "At the molecular level, IGF2BP3 regulates a complex posttranscriptional operon governing leukemia cell survival and proliferation." (PMID 34321607, 2022). "The role of IGF2BP3 in such cells and in relapse of leukemia is of great interest and a future direction for our work." (PMID 34321607, 2022). "Positivity (>1%) to IGF2BP3 was detected in 74 out of 83 patients (89%), while the proportion of positively stained leukemia cells ranged from 1 to 100% (median 34%)." (PMID 33805930, 2021). "IGF2BP3 plays a critical role in regulating cell proliferation via an IGF2-dependent pathway in K562 leukemia cells." (PMID 28771592, 2017). "Taken together, these data suggest the intriguing hypothesis that IGF2BP3 rewrites the epitranscriptome in leukemia cells." (PMID 41015030, 2025). "The depletion of IGF2BP3 results in to decreased expression of both full‐length variants and alternatively spliced variants (shorter variant) for Cd69, Hoxa7 and Hoxa9, suggesting that IGF2BP3 serves as a critical regulator and a potential therapeutic target for MLL‐Af4‐driven leukaemia." (PMID 37850412, 2023). "Here, we have shown the central importance of the RBP IGF2BP3 in MLL-AF4-driven leukemia." (PMID 34321607, 2022). "We investigated whether IGF2BP3 regulates RCC2 expression by modulating its mRNA stability in leukemia cells." (PMID 35217832, 2022). "Furthermore, flow cytometric analysis showed that IGF2BP3 overexpression decreased the apoptosis of leukemia cells and that the percentage of Annexin V + cells was reduced." (PMID 35217832, 2022). "IGF2BP3 stabilises the activity of a known cancer-related protein, promoting leukemia progression." (PMID 35217832, 2022). "Additionally, IGF2BP3 knockdown significantly promoted apoptosis in leukemia cells, as evidenced by the higher percentage of Annexin V + cells." (PMID 35217832, 2022). "Moreover, Igf2bp3 knockout accelerated the onset of leukemia by MLL-AF10 in vivo in our experimental settings (p = 0.0377)." (PMID 36335100, 2022). "To determine how IGF2BP3 modulates gene expression in MLL-Af4 leukemia, we performed eCLIP-seq." (PMID 34321607, 2022). "We propose that IGF2BP3 may prove to be a valuable therapeutic target in MLL-AF4 leukemia, given its function in the pathogenesis of this unique molecular subtype of acute leukemia." (PMID 34321607, 2022). "IGF2BP3 did not only show increased expression in MLL-positive B-ALLs but a treatment with I-BET151, which has been described as effective treatment for MLL-positive leukemias, showed a dose-dependent reduction of IGF2BP3 as well as a stagnation of the leukemic cells in the G1-S phase." (PMID 32408494, 2020). "Furthermore, inhibiting the RNA binding protein IGF2BP3 may also increase the efficacy of MIs in MLLr leukemias, as knocking down IGF2BP3 enhances the differentiation of MLL-AF4 leukemia cells following treatment with MI-503." (PMID 39336822, 2024). "In addition, IGF2BP3 plays a role in MLL-rearranged leukemia." (PMID 37298373, 2023). "Hence, IGF2BP3 regulates multiple pathways known to be important in MLL-AF4 leukemia." (PMID 34321607, 2022).
leukemia (continued). "However, oncofetal RBPs such as LIN28B and IGF2BP3 allow specific targeting in MLL-r leukemia cells and, thus, could be particularly valuable therapeutically." (PMID 36307883, 2022). "Hence, the net effect of IGF2BP3 may be multipronged—with a strong impact on steady-state mRNA levels and an additional impact on splicing—in leukemia stem and progenitor cells." (PMID 34321607, 2022). "IGF2BP3 re-expressing mice displayed significantly higher counts for CD11b+, lineage− cells, and LSK (Lin− ckit+Sca1−) cells, including a potential leukemia-initiating cell (LIC) population, in both bone marrow and spleen (respectively)." (PMID 41015030, 2025). "In leukaemia, IGF2BP3 helps stabilize COX‐2 mRNA and facilitates the translation of the key mediators of inflammatory and antiapoptotic signals in leukaemia cells." (PMID 38358034, 2024). "Combining menin inhibitors with depletion of IGF2BP3 impairs cell growth and increases differentiation of KMT2A::AFF1 leukemia." (PMID 38601080, 2024). "To identify differentially expressed transcripts, we sequenced RNA from WT/MLL-Af4 and I3KO/MLL-Af4 Lin− and CD11b+ bulk leukemia cells after confirming expression of MLL and Igf2bp3." (PMID 34321607, 2022). "Since Igf2bp3 deletion reduces LIC numbers and impairs LIC function, we next determined if Igf2bp3 affects LIC capability to initiate MLL-Af4 leukemia in vivo." (PMID 34321607, 2022). "Here, we find that the RNA-binding protein IGF2BP3, which is overexpressed in MLL-translocated leukemia, strongly amplifies MLL-Af4-mediated leukemogenesis." (PMID 34321607, 2022). "We then showed that IGF2BP3 is overexpressed in AML and plays an essential role in regulating leukemia cell proliferation in vivo and ex vivo." (PMID 35217832, 2022). "Deletion of Igf2bp3 significantly increased survival of MLL-Af4 transplanted mice and decreased the numbers and self-renewal capacity of MLL-Af4 leukemia-initiating cells (LICs)." (PMID 34321607, 2022). "Overall, a direct interaction between IGF2BP3 and IGF2, with a consequent promotion of cell proliferation in vitro, has been demonstrated in leukemia, thyroid cancer, and glioma." (PMID 32010687, 2019). "The lineage of the leukemia induced by MLL-Af4 in mice may be a limitation of the study, as we cannot conclude an in vivo function for Igf2bp3 in murine B-ALL." (PMID 34321607, 2022). "Here, we will focus on IGF2BP3, which is specifically overexpressed in MLL-r leukemia." (PMID 36307883, 2022). "In addition, IGF2BP3 contributes to stabilizing COX-2 mRNA, favoring the translation of this crucial mediator of inflammation and antiapoptotic signals in leukemia cells." (PMID 32010687, 2019). "IGF2BP3 (alias IMP3), represses translation of IGF-2 during late embryonic development in mice and humans, and has been shown to promote the translation of IGF-2 leader 3 mRNA in a cell model of leukemia." (PMID 23936243, 2013). "It is not clear if IGF2BP3 may play a role in other leukemia subtypes given its relatively restricted pattern of expression in MLL-translocated leukemia." (PMID 34321607, 2022). "The correlation network of survival-related SFs and AS events identified IGF2BP3 as the only SF that correlated with AS events, and most important, IGF2BP3 has been clinically relevant in leukemia, while its specific molecular mechanism in AML has not been clearly deciphered." (PMID 34212178, 2021). "Additionally, we used the external database Oncomine to analyze the expression of IGF2BP3 in AML patients/samples, and the expression of IGF2BP3 was observed to be upregulated compared with that in the normal controls in the Andersson Leukemia and Haferlach Leukemia cohorts." (PMID 35217832, 2022). "Furthermore, enforced expression of another MLL fusion protein, MLL-AF9, and other non-MLL leukemia drivers, including AML1-ETO, MYC, and NRAS in primary HSPCs, show that the upregulation of Igf2bp3 is specific to MLL-Af4." (PMID 34321607, 2022).
glioblastoma (24 papers, 2011 to 2025). The most malignant astrocytic tumor (WHO grade IV). "IGF2BP1, IGF2BP2 and IGF2BP3 are dysregulated in many tumor types, being associated with chemoresistance in glioblastoma, ovarian and colorectal cancer." (PMID 40061896, 2025). "Both METTL1 and IGF2BP3 are highly expressed in glioblastoma, and their upregulations are associated with poor survival in patients." (PMID 39198433, 2024). "Gain and loss of function studies in glioblastoma cells established the role of IGF2BP3 in promoting proliferation, anchorage-independent growth, invasion, and chemoresistance." (PMID 35625706, 2022). "Previously, IGF2BP3 has been reported to be a diagnostic tool for bile duct carcinoma and glioblastoma." (PMID 29212181, 2017). "In a study investigating glioblastoma survival, igf2bp3 was found to have gender association." (PMID 24548546, 2014). "At the same time, Valproic Acid, Cadmium, Pulmonary Fibrosis, Glioblastoma, IGF2BP3, Curcumin, Cisplatin, Cyclosporine, Quercetin, and Tretinoin show an interaction relationship centred on EGF." (PMID 40461634, 2025). "The study observed a decrease in CDK1 expression as well as an arrest of glioblastoma cells in the G0/G1 phase upon IGF2BP3 knockdown, underscoring the vital role of IGF2BP3 in cell cycle regulation." (PMID 38398118, 2024). "Similar to METTL1, IGF2BP3 is highly expressed in tumors compared to normal tissues across various cancer types, with glioblastoma ranked second." (PMID 39198433, 2024). "A recent study evaluated the impact of IGF2BP3 on the proliferation of glioblastoma cells by using IGF2BP3 shRNAs." (PMID 38398118, 2024). "For example, IGF2BP3 is known to have angiogenic activity in glioblastoma and giant cell tumor, and more refined assays investigating these aspects should be foreseen in future studies." (PMID 32659970, 2020). "In addition, elevated levels were observed for RBM15B, WTAP, FTO, YTHDF2, YTHDF3, IGF2BP2, and IGF2BP3 in glioblastoma samples compared with normal brain controls." (PMID 38398118, 2024). "Notably, among the proteins involved in m7G regulation in glioblastoma, IGF2BP3 is the most upregulated one in tumor versus normal tissues." (PMID 39198433, 2024). "Consequently, the knockdown of IGF2BP3 effectively restrained the tumorigenic properties of glioblastoma in a mouse model." (PMID 38398118, 2024). "IGF2BP3 has well-known roles in a number of cancers, including as a glioblastoma marker." (PMID 33426524, 2020). "Furthermore, IGF2BP3 was found to act as an oncogenic factor promoting proliferation and invasion of glioblastoma via activating PI3K/MAPK pathway." (PMID 33094561, 2020). "Researchers identified that miR-129-1 acted as a tumor suppressor and could block the cell cycle of glioblastoma multiforme by targeting IGF2BP3 and MAPK38." (PMID 31624237, 2019). "In glioblastoma, the methylation level and the half lifetime of the modified transcript could be modulated by tuning IGF2BP3, or by site-specific targeting of m7G through a dCas13b-guided system, resulting in modulation of cancer progression and chemosensitivity." (PMID 39198433, 2024). "Functional assay confirmed IGF2BP3 as a target of miR-129-1, while targeting of IGF2BP3 by miR-129-1 decreases the MAPK/ERK and PI3K/AKT cascade which leads to the postponement of G1-S transition in the cell cycle in glioblastoma cells." (PMID 35625706, 2022). "MiR‐129–1, as a negative regulator of IGF2BP3 and MAPK1, participates in cell cycle arrest in glioblastoma and acts as a potential tumor suppressor." (PMID 34029007, 2021).
glioblastoma (continued). "The mRNA and protein expression of IGF2BP3 is up-regulated in glioblastomas but not in lower-grade astrocytomas." (PMID 35625706, 2022).
lung adenocarcinoma (24 papers, 2015 to 2025). A carcinoma that arises from the lung and is characterized by the presence of malignant glandular epithelial cells. "Meanwhile, IGF2BP3 also overexpressed as well as associated with poor OS in various tumors, such as kidney renal papillary cell carcinoma and lung adenocarcinoma." (PMID 32993738, 2020). "Finally, by integrating the results of PPI network analysis and one-way COX regression analysis, we identified six RBPs that are both DEGs and associated with lung adenocarcinoma prognosis—IGF2BP3, SNRPE, GAPDH, MRPL12, MRPL15, and INTS8, with IGF2BP3 being the most differentially expressed." (PMID 40801655, 2025). "The results indicate a notable upregulation of IGF2BP3 expression in paired lung adenocarcinoma tissues when compared to normal tissues." (PMID 40801655, 2025). "Next, we knocked down IGF2BP3, which significantly inhibited lung adenocarcinoma cell proliferation and induced apoptosis, suggesting its pro-carcinogenic function." (PMID 40801655, 2025). "Experimental data demonstrate that IGF2BP3 knockdown significantly inhibits the proliferation of lung adenocarcinoma cells, enhances apoptosis, and induces G2/M phase cell cycle arrest." (PMID 40801655, 2025). "Subsequent analysis demonstrated that IGF2BP3 levels were markedly elevated in individuals diagnosed with mid-to-late stage lung adenocarcinoma, starkly contrasting with those in the early stages of the condition." (PMID 40801655, 2025). "IGF2BP3, which is highly expressed in lung adenocarcinoma (LUAD), inhibits ferroptosis by binding to key ferroptosis-related proteins such as GPX4, SLC3A2, ACSL3, and FTH1, making it a promising target for anticancer therapies." (PMID 40271153, 2025). "This study identifies LINC01559 as a novel ceRNA that drives osimertinib resistance in lung adenocarcinoma by sponging miR-320a to enhance IGF2BP3 expression." (PMID 40313617, 2025). "Although the function of IGF2BP3 in a variety of cancers has been preliminarily revealed, its specific mechanism of action in lung adenocarcinoma and the clinical relevance of IGF2BP3 remain to be fully elucidated through additional research." (PMID 40801655, 2025). "RNA-binding proteins (RBPs), particularly IGF2BP3, play critical but underexplored roles in lung adenocarcinoma (LUAD)." (PMID 40801655, 2025). "Taken together, these results indicate that IGF2BP3 is highly expressed in multiple cancer tissues, especially in lung squamous cell carcinoma and lung adenocarcinoma." (PMID 32984260, 2020). "Measurementof canonical HIF targets showed that IGF2BP3 depletion attenuated the endogenousexpression of HIF target genes in H1299 lung adenocarcinoma cells." (PMID 26567849, 2015). "Survival analysis demonstrated that IGF2BP3 serves as an independent predictor for lung adenocarcinoma prognosis, and the Normogram model constructed based on its expression level and clinical features has significant clinical value in predicting patient survival." (PMID 40801655, 2025). "Although our results confirm that IGF2BP3 is a key driver of lung adenocarcinoma progression and a potential therapeutic target, its role needs to be elucidated in the context of other genes that have been clearly identified as having prognostic or therapeutic significance in LUAD." (PMID 40801655, 2025). "Further GSEA analysis indicated that genes associated with CD4+ Tem cells were significantly downregulated, whereas elevated IGF2BP3 expression correlated with increased Th2-related gene activity, suggesting its potential role in lung adenocarcinoma by influencing immune cell infiltration." (PMID 40801655, 2025). "In conclusion, IGF2BP3 might be crucial in lung adenocarcinoma development through its regulation of cell cycle and metabolic pathways." (PMID 40801655, 2025). "In addition, compared with normal tissues, IGF2BP3 was up-regulated in many tumors, including lung adenocarcinoma, ovarian cancer, breast invasive cancer, bladder urothelial carcinoma and so on." (PMID 34737950, 2021).
lung adenocarcinoma (continued). "By “oncoppredict”, BI-2536 has potential therapeutic value for patients with low IGF2BP3 expression, which provides a reference for precise clinical treatment—not only as a prognostic biomarker and immunotherapy predictor, but also as a potential therapeutic target in lung adenocarcinoma treatment." (PMID 40801655, 2025). "This indicates IGF2BP3 may be crucial in the initiation and progression of lung adenocarcinoma." (PMID 40801655, 2025). "IGF2BP3 activates Notch signaling in an m6A-dependent manner, triggering partial epithelial-mesenchymal transition (EMT) in lung adenocarcinoma cells." (PMID 40271153, 2025). "In conclusion, we identified GULPsig, consisting of IGF2BP1, IGF2BP3, SMC1B, CLDN6, and LY6K, as a potential prognostic signature for lung adenocarcinoma patients." (PMID 37655157, 2023). "For instance, in lung adenocarcinoma, high HNRNPC and IGF2BP3 levels correlate with reduced overall survival, and a six-gene risk signature (KIAA1429, ALKBH5, METTL3, HNRNPC, YTHDC2, and YTHDF1) strongly correlated with various clinical and pathological features." (PMID 36831575, 2023). "The results revealed that the levels of IGF2BP1, particularly IGF2BP2 and IGF2BP3, were remarkably upregulated in many cancer types such as bladder urothelial carcinoma (BLCA), liver hepatocellular carcinoma (LIHC), lung adenocarcinoma (LUAD), and lung squamous cell carcinoma (LUSC)." (PMID 35003212, 2021). "For instance, IGF2BP1 and IGF2BP3 showed an oncogenic role in KIRC and lung adenocarcinoma (LUAD)." (PMID 33718187, 2021). "IGF2BP3 could stabilize a spectrum of anti-ferroptosis mRNA, including glutathione peroxidase 4 (GPX4), solute carrier family 3 member 2 (SLC3A2), acyl-CoA synthetase long chain family member 3 (ACSL3), and ferritin heavy chain 1 (FTH1), to inhibit ferroptosis in lung adenocarcinoma cells." (PMID 37554271, 2023). "Additionally, overexpression of IGF2BP3 also indicated poor OS in various tumors, including kidney renal clear cell carcinoma (KIRC), kidney renal papillary cell carcinoma (KIRP), brain lower grade glioma (LGG), lung adenocarcinoma (LUAD), mesothelioma (MESO) and sarcoma (SARC)." (PMID 32993738, 2020).